TLR7 (toll like receptor 7)
Diseases named in the same sentence as TLR7 in open-access papers (continued):
Sharing a sentence is not in itself a finding about the gene and the disease.
HIV-1 infection (continued). "In summary, our study shows strong correlation of TLR7 rs179010 minor allele T and haplotype TTA with decreased susceptibility and slow progression of HIV-1 infection in acute phase, which could be partly due to restriction of viral load, and influence of the set point." (PMID 33193416, 2020). "We also found that the TLR7 rs179009 major allele A seems to function as a risk factor for rapid progress and poor prognosis in the acute phase of HIV-1 infection, while its minor allele G could be a risk factor for the chronic course of HIV-1 infection." (PMID 33193416, 2020). "Therefore, we speculate that this TFBS polymorphism affects the timing of TLR7 expression, which need stimulation to elicit TLR7 expression and the following high secretion of IFNα in acute phase of HIV-1 infection." (PMID 33193416, 2020). "We identified a subset of four miRNAs that were significantly up-regulated in cells stimulated through TLR3 and TLR4 but not through TLR7 and could potentially play a role in modulating susceptibility to HIV-1 infection in this system." (PMID 23028330, 2012). "As an example, agonists for TLR3, TLR7, TLR8, and TLR9 have been shown to be capable of inhibiting HIV-1 infection and induced IFN-α-stimulated gene expression in PBMCs in vitro." (PMID 38994942, 2024). "Increased expression of TLR6, TLR7, and TLR8 mRNA has been observed in chronic untreated HIV-1 infections." (PMID 37298575, 2023). "Understanding the mechanisms controlling the expression of TLR7 and the production of IFN-I is therefore an important issue in HIV-1 infection, in particular for the development of new strategies for viral eradication." (PMID 36271499, 2022). "Plasmacytoid dendritic cells highly express TLR7, which greatly enhances their ability to produce IFN-I up to 1,000-fold more than other cell types’ response to HIV-1 infection." (PMID 29163506, 2017). "HIV-1 infection induces pDCs to produce a broad range of type I IFN through the activation of Toll-like receptors 7 and 9 (TLR7 and TLR9)." (PMID 21176220, 2010). "In spite of the reduced circulating IFN-α levels and impaired production upon TLR9 and/or TLR7 stimulation in vitro, there is increasing evidence of increased IFN-α production in vivo during HIV-1 infection." (PMID 19936055, 2009). "Prior addition of TLR3, TLR7, TLR8, and TLR9 agonists was shown to inhibit HIV-1 infection in peripheral blood mononuclear cells (PBMCs); TLR8 and TLR9 agonists were found to be more effective in blocking HIV-1 replication, along with the activation of other antiviral sensors." (PMID 37298575, 2023). "Based on the recent study, the author will also propose that the higher propensity of female pDCs to produce IFN-I in response to TLR7 stimulation is unlikely to contribute to the sex differences in an acute HIV-1 infection." (PMID 34512664, 2021). "During HIV-1 infection in human primary plasmacytoid DCs, autophagy plays a key role in presenting the HIV-1 RNA genome to its cognate immune receptor Toll-like receptor-7 (TLR7) in endosomes, leading to the induction of IFNα." (PMID 30510929, 2018). "In contrast to MFI, the frequency of BDCA-2+ pDCs is not influenced by HIV-1 infection, and in vitro activation of pDC via TLR7/9 agonists leads to downregulation of the pDC surface-localized BDCA-2." (PMID 29597250, 2018). "The fact that the restriction was not induced by HIV-1 infection itself argues that the viral RNA is shielded upon uncoating, preventing sensing in monocytes by TLR7/8." (PMID 27905985, 2016). "In conclusion, both TLR7 and TLR9 responses are impaired in HIV-1 infection." (PMID 22470494, 2012). "We also demonstrate that miR-155 is selectively up-regulated upon TLR3/4- but not TLR7-stimulation, and that specific inhibition of miR-155 partially restores HIV-1 infection in poly(I∶C)-stimulated MDMs." (PMID 23028330, 2012).
HIV-1 infection (continued). "DCs sustain long-term productive HIV-1 infection, and more recently, in vivo findings have verified that lymph node DCs of individuals on antiretroviral therapy (ART) harbor inducible, replication-competent proviruses that can be reactivated by TLR7/8 stimulation." (PMID 41596493, 2026). "Furthermore, HIV-1 infected individuals have aberrant TLR7 expression in CD8+ T cells, which may contribute to inappropriate immunological activation in HIV-1 infection and play a key role in the HIV-1 pathogenesis." (PMID 34659656, 2021). "Additionally, in contrast to peripheral CD4 T cells, HIV-1 infection does not induce the expression of TLR7 in splenic CD4 T cells or macrophages." (PMID 30867315, 2019). "Interestingly, recent data from the non-human primate model of HIV-1 infection provided additional support for a role of the TLR7 pathway in HIV-1 pathogenesis." (PMID 26056580, 2014). "Conversely, non-specific stimulation of B cells via TLR7 could contribute to polyclonal B cell activation and exhaustion during HIV-1 infection." (PMID 21998589, 2011). "Thus, we assessed inflammasome activation by HIV-1 infection or VbP treatment with and without pretreating THP-1 cells with agonists of TLR1/2 (Pam3CSK4), TLR7/8 (CL075), TLR8 (TL8-506), or TLR4 (LPS)." (PMID 37417868, 2023). "At this point, HIV-1 infection resulted in a trend toward suppression of Toll-like receptor 3 (TLR3) protein expression on splenic but not peripheral CD4 T cells, whereas peripheral TLR7 and TLR9 protein expression was elevated after HIV-1 infection of both CD4 T cells and macrophages." (PMID 30867315, 2019).
Sepsis (32 papers, 2011 to 2025). Sepsis is defined as life-threatening organ dysfunction caused by a dysregulated host response to infection. "Building on this premise that EV cargo is modified during sepsis and is associated with disease severity—potentially altering EV activity—we silenced TLR7 in our sepsis model and determined the impact on septic EV biological function." (PMID 41301522, 2025). "Our prior work demonstrates that TLR7 deficiency results in a protective effect against sepsis-induced thrombocytopenia." (PMID 41301522, 2025). "Further, we have shown that TLR7 genetic deficiency (TLR7−/−) in sepsis results in decrease inflammation, organ injury, and mortality." (PMID 41301522, 2025). "Excessive inflammation in sepsis creates an environment for the overactivation and functional exhaustion of peripheral innate immune cells, and TLR7 deficiency appears to be protective in this regard." (PMID 41301522, 2025). "In patients with SARS-CoV2-associated sepsis, TLR7-Band 3 interactions in the RBC membrane are increased when compared with healthy controls." (PMID 38982195, 2024). "Immunofluorescence and qPCR showed that TLR7 deficiency reduced the expression of Serca and RyR2 in response to sepsis." (PMID 33463061, 2021). "Future research will investigate changes in EC–platelet–monocyte interactions, septic EV function and cargo, and the impact of TLR7 deficiency, and whether our findings can be replicated with pharmacological inhibition of TLR7 in sepsis." (PMID 41301522, 2025). "On the other hand, TLR7 deficiency exacerbates systolic dysfunction in response to sepsis." (PMID 33463061, 2021). "This suggested that TLR7 deficient micehad reduced Ca2+ transient in response to sepsis." (PMID 33463061, 2021). "Thus, TLR7 association with RBC membrane proteins is increased during SARS-CoV-2-induced sepsis." (PMID 38982195, 2024). "Therefore, we asked if TLR7-Band 3 associations are increased in RBCs from patients with sepsis." (PMID 38982195, 2024). "We have reported that plasma EVs and TLR7 play a role in systemic inflammation in polymicrobial sepsis." (PMID 41301522, 2025). "Our primary objective is to provide evidence for the role of TLR7 in modulating hemostatic platelet functions to identify a novel signaling pathway contributing to platelet dysfunction and coagulopathy in sepsis." (PMID 41301522, 2025). "Sepsis was induced in wild-type (WT) and TLR7-deficient (TLR7−/−) mice by cecal ligation and puncture." (PMID 41301522, 2025). "In this current study, we specifically present investigations into the impact of TLR7 on platelet aggregation and adhesion in sepsis, as well as the involvement of TLR7 in EV-mediated platelet activation." (PMID 41301522, 2025). "The innate immune single-stranded RNA sensor, Toll-like Receptor-7 (TLR7), plays a key role in thrombocytopenia in sepsis." (PMID 41301522, 2025). "A major finding of our study is the impact of TLR7 signaling on the development of platelet dysfunction in sepsis." (PMID 41301522, 2025). "Next, we narrowed our focus and tested the impact of TLR7 on plasma EVs as a downstream effector in sepsis." (PMID 41301522, 2025). "The findings indicate that TLR7 activation in sepsis drives inflammation, which alters the functional character of plasma EVs, promoting platelet activation and exhaustion." (PMID 41301522, 2025). "Recent studies in knockout (KO) mice clearly demonstrate the mechanistic role that miR‐146a and the single‐stranded RNA sensor TLR7 play in sepsis‐induced inflammation and organ injury." (PMID 38014923, 2024). "While TLR7-Band 3 interactions in RBCs from healthy donors were detected by distinct PLA punctae, RBCs from patients with COVID-associated sepsis exhibited a robust PLA signal with aggregates of PLA punctae." (PMID 38982195, 2024).
Sepsis (continued). "Macrophages are also susceptible to extracellular miRNA signaling via the toll-like receptor 7 (TLR7) pathway, which can result in a cytokine storm and end organ injury in mouse models of trauma and sepsis." (PMID 38534389, 2024). "Recently, it was proposed and confirmed in sepsis mouse model that miRNAs from sepsis plasma Exos promote inflammation by inducing cytokine production via TLR7-MyD88 signaling." (PMID 33533957, 2022). "This study aims to determine the role of TLR7 in cardiac dysfunction during sepsis and explore the mechanism of TLR7 in septic cardiomyopathy." (PMID 33463061, 2021). "Their group reported the protective effect of intraperitoneal injection of the TLR4 or TLR7/8 agonist 24 h prior to the initiation of sepsis, resulting in increased survival and reduced bacteremia via enhanced peritoneal neutrophil recruitment." (PMID 34945120, 2021). "Western blot analysis indicated that the expression of phosphorylated PLN in Serine 16 instead of Threonine 17 decreased in TLR7−/− mice in response to sepsis compared with WT mice, along with downregulation of phosphorylated PKA." (PMID 33463061, 2021). "The current study indicated that the inhibition of PKA abrogated TLR7's cardioprotective effects in response to sepsis." (PMID 33463061, 2021). "To validate the expression of TLR7 in septic cardiomyopathy, we investigated the expression of TLR7 in the mouse models of sepsis and NRVMs in response to LPS." (PMID 33463061, 2021). "Herein, our data showed that TLR7 expression was upregulated in cardiomyocytes in response to sepsis, and TLR7 activation further activates the cAMP‐PKA pathway in the sarcoplasmic reticulum." (PMID 33463061, 2021). "TLR7 protected against sepsis‐induced cardiac dysfunction through activation of cAMP‐PKA‐PLN pathway." (PMID 33463061, 2021). "(2016) reported that splenic cellular RNAs and miR‐146a are released into the circulation during polymicrobial sepsis and activate innate immune signaling via the TLR7 pathway." (PMID 28665028, 2017). "To gain insight into the function of this pathway during lung infection, we also characterized the phenotype of Tlr7−/− mice during respiratory infection with Y. pestis CO92, a pgm+ strain that causes fulminant bronchopneumonia along with secondary sepsis." (PMID 28847850, 2017). "CD11b+ cells in the spleens of wild type mice constitutively express TLR7, and TLR7’s expression is highly up regulated during sepsis." (PMID 21966467, 2011). "This increase in pathogen control and inflammation demonstrate that TLR7 signaling will overcome the inhibitory phenotype predominant during sepsis." (PMID 21966467, 2011). "We then tested an alternative hypothesis that upstream TLR7 signaling in sepsis impacts downstream plasma EV-mediated platelet activation and PLA formation." (PMID 41301522, 2025). "This study investigated whether TLR7 signaling also contributes to platelet dysfunction in sepsis, and whether the bioactivity of downstream inflammatory mediators, specifically extracellular vesicles (EVs), is impacted by the TLR7 signaling pathway." (PMID 41301522, 2025). "Additionally, the absence of TLR7 signaling resulted in reduced EV-mediated platelet activation, indicating a potential connection between upstream TLR7 signaling, inflammation, and downstream pathological EVs in sepsis." (PMID 41301522, 2025). "TLR7 recognizes single-stranded RNAs and has a nuanced role in polymicrobial sepsis." (PMID 41301522, 2025). "We observed TLR7- Band 3 proximity that was enhanced in patients with COVID-associated sepsis when compared with non-COVID septic patients and healthy control subjects." (PMID 38982195, 2024). "Moreover, the examination of caspase‐3 activity indicated the minimal difference between WT and TLR7−/− mice which were attributed to sepsis." (PMID 33463061, 2021). "Herein, we demonstrated that the activation of TLR7 improved sepsis‐induced septic cardiomyopathy." (PMID 33463061, 2021).
Sepsis (continued). "Therefore, we demonstrated that TLR7 protected against sepsis‐induced Ca2+ handling by enhancing the cAMP/PKA levels." (PMID 33463061, 2021). "We found that TLR7 knockout markedly exacerbated sepsis‐induced systolic dysfunction." (PMID 33463061, 2021). "Also, splenic RNA and miR‐146a are released into the circulation during polymicrobial sepsis and promote the production of complement factor B via TLR7 signaling." (PMID 28665028, 2017). "From this analysis, it appears there could be early bacterial clearance in the lungs of Tlr7−/− mice that may directly or indirectly impact bacterial dissemination and the onset of sepsis." (PMID 28847850, 2017). "We hypothesize that EVs signal in part via TLR7 to induce platelet activation in sepsis." (PMID 41301522, 2025). "It has previously been demonstrated that TLRs such as TLR-2, TLR-3, TLR-4, and TLR-7 are highly expressed in the lung tissues of septic mice, therefore suggesting a potential role in the pathogenesis of ARDS during sepsis." (PMID 40076895, 2025). "Extracellular vesicles that contain miRNAs in sepsis induce macrophages into the production of inflammatory cytokines via TLR pathways, specifically TLR7/MyD88." (PMID 38534389, 2024). "miR-146a-5p-mediated activation of TLR7 induces TNF, pulmonary inflammation, endothelial barrier disruption and ARDS in sepsis mice." (PMID 35990654, 2022). "In fact, this has been implied in our previous work that demonstrated plasma EVs isolated from sepsis mice promoted significant CXCL2 and IL-6 via miRNA- and TLR7-dependent mechanisms." (PMID 32958516, 2020). "During sepsis, exosomes contribute to the progression of inflammation by carrying proinflammatory cytokines (such as IL-1β, IL-6, TNF-α) and activating Toll-like receptors (TLR2, TLR4, TLR7) in immune cells." (PMID 41268545, 2025). "Of note, LPS scarcely induced Stat1 and Tlr7 expression in Tyk2−/−cells, supporting the idea of a downregulated inflammation leading to the lack of sepsis described in Tyk2−/− mice in response to LPS." (PMID 38683377, 2024). "Interestingly, Toll‐like receptor signalling was detected in sepsis, specifically in the brain (prefrontal cortex and hippocampus), via the upregulation of genes such as CD14, TLR1, TLR2, TLR3, TLR7, IRAK3 and IRAK4." (PMID 37731199, 2023). "The IRAK1 gene is the key encoder of the intracellular signaling pathway of TLR/IL-1R and assists the recognition of viruses by TLR7/8 and the production of IFN- α, being one of the main genes that contribute to the divergence of responses related to gender after trauma and sepsis." (PMID 33791232, 2021). "In addition, in a neonatal mouse model of sepsis, the use of immunomodulatory agents, including Toll like receptor 4 (TLR4) or TLR7/8 agonists, aluminum salt-based adjuvants, and Bacille Calmette-Guérin (BCG), have been investigated extensively." (PMID 34945120, 2021). "The antimalarial drugs, hydroxychloroquine sulfate and chloroquine, were found to inhibit the endosomal TLR signaling (TLR7/8/9) by modulating the endosomal acidification, but their efficacy in treating sepsis or virus‐induced ALI/ARDS has not been clearly defined yet." (PMID 37078808, 2023). "Our data demonstrated that activation of TLR7 protected against sepsis‐induced cardiac dysfunction through promoting cAMP‐PKA‐PLN pathway, and we revealed that TLR7 might be a novel therapeutic target to block the septic cardiomyopathy and support systolic function during sepsis." (PMID 33463061, 2021). "Murine models of sepsis-induced ALI mimic TLR3, TLR4, TLR7 and NLRP3 activation but, unlike the human disease, also activate TLR2 and TLR9." (PMID 33672738, 2021). "In sum, all that can be said in general about innate activation in sepsis is that TLR2, TLR4, TLR5, TLR7 and NLRP3 can be, but are not necessarily, activated, while TLR9 may or may not be downregulated." (PMID 33672738, 2021).